GDF15 (growth differentiation factor 15)
Diseases named in the same sentence as GDF15 in open-access papers (continued):
Sharing a sentence is not in itself a finding about the gene and the disease.
tumor (continued). "Notably, CAF-FAP and CAF-C7 both showed upregulated chemokine signaling pathway, but showed high expression of pro-inflammatory genes (CCL2, CXCL12, GDF15, and LIFR) at tumor core and pro-fibrotic genes (TNFRSF12A, TGFBR1, TGFBR2) at FR, respectively." (PMID 39870619, 2025). "Macrophage inhibitory factor-1, also known as growth differentiation factor 15 (GDF15), belongs to the TGF-β superfamily and is linked to the activation of many tumor-promoting pathway, but has not been studied in depth in HNSCC." (PMID 41035818, 2025). "Gdf15 mRNA levels were not altered in peripheral tissues or at the tumor site, even at an early stage of cachexia." (PMID 40124481, 2025). "Regarding tumour size, only MFGE8 expression showed a significant correlation, while DJ-1 and GDF15 did not exhibit statistically meaningful associations." (PMID 41009755, 2025). "Additionally, the binding between GDF15 and CD48 accumulates FOXP3 in Tregs, enhancing its tumor-suppressing functions." (PMID 40144214, 2025). "Nonetheless, other studies involving tumor-bearing mice with persistently elevated endogenous GDF15 suggest no change in EE, highlighting the potential role of fluctuating versus steady-state GDF15 levels in modulating metabolism." (PMID 40837873, 2025). "Both NAG-1/GDF15 and pro-NAG-1/GDF15 greatly reduced tumor size." (PMID 40316530, 2025). "Comparison of gene expression levels between these groups may provide insights into the potential roles of DJ-1, GDF15, and MFGE8 in tumour progression, malignant transformation, and poor prognosis." (PMID 41009755, 2025). "Some studies have found that increased expression of GDF-15 significantly inhibited the proliferation of NSCLC cells, suggesting that it may have a tumor-suppressive effect." (PMID 40144214, 2025). "Finally, GFRAL knockdown in tumor cells inhibited GDF15-induced TNF-α and EGF expression, confirming GFRAL as the mediator of GDF15 downstream signaling." (PMID 41035818, 2025). "Furthermore, CAFs secrete various cytokines, exosomes, and growth factors, such as leukemia inhibitory factor (LIF) and growth differentiation factor 15 (GDF15), which further drive tumor growth and invasion." (PMID 38920700, 2024). "Immunohistochemistry also showed that treatment with SNCSS(Cas9/sgGDF15) reduced the expression level of GDF15 in tumor tissues, but did not affect the expression level of Ki67." (PMID 38704691, 2024). "Conversely, in EHE cells GDF-15 knockdown failed to affect tumor take and growth kinetics in SCID mice possibly because we worked with human tumor cells in the context of the murine microenvironment of immunodeficient mice." (PMID 39283723, 2024). "CSCs release galectin-3, growth differentiation factor 15 (GDF-15), interleukin-10 (IL-10), interleukin-13 (IL-13), prostaglandin E2 (PGE2), and transforming growth factor-beta (TGF-β), which are known to modulate the tumor niche." (PMID 38920716, 2024). "MIC-1/GDF-15, similar to TGF-β, has a complex effect on tumor behavior." (PMID 38335385, 2024). "Our results might suggest an influence of the immunomodulatory cytokines CCL5, CCL18, GDF15, and TGFB1 on tumor progression." (PMID 39272860, 2024). "The immunohistochemical evaluation of infiltrating CD8+ T cells from this experiment indicated a synergistically enhanced T cell recruitment by anti-PD-1 and anti-GDF-15, with significantly (p = 0.0033) increased CD8+ T cell counts next to necrotic tumor areas." (PMID 37474523, 2023). "Utilizing paired t’-test, we discovered that GDF15 expression level was not statistically different between the tumor and paired normal samples in TCGA-KICH and TCGA-KIRP." (PMID 38082448, 2023). "High GDF-15 serum levels thus indicate aggressive tumors that respond poorly to anti-PD-1 therapy, irrespective of tumor load." (PMID 37474523, 2023).
tumor (continued). "There was no statistical difference in median GDF15 based on specific tumor type, although the study was not powered to detect a difference between specific diagnoses (p=0.150)." (PMID 38146512, 2023). "Immunohistochemistry from tumor-bearing mice euthanized after 28 to 33 days showed that transgenic human GDF-15 reduced spontaneous CD8+ T cell infiltration (p = 0.024) without altering the total number of tumor-infiltrating leukocytes (p = 0.91)." (PMID 37474523, 2023). "In addition, GSC-secreted factors such as VEGF-A, GDF15, IL8, and miR21 also have been shown to induce tumor angiogenesis." (PMID 35642785, 2022). "Moreover, hepcidin expression is regulated by growth differentiation factor 15 (GDF-15), secreted by tumor microenvironment cells." (PMID 35334593, 2022). "In our study, the GDF-15 knockdown experiment using siRNAs revealed that decreased pro-GDF-15 suppressed lidocaine-induced growth inhibition of HeLa cells, indicating that lidocaine-induced pro-GDF-15 might play a significant role in tumor suppression." (PMID 36008442, 2022). "GDF-15 levels did not change 24 hours after milademetan administration on day 21 of dosing, likely due to reduced tumor sizes." (PMID 35801592, 2022). "Serum GDF-15 was found to be an independent marker of the presence of higher-grade (GS ≥ 7) tumors, which was not solely due to tumor burden." (PMID 33995654, 2021). "Growth and differentiation factor 15 (GDF‐15), also known as macrophage inhibitory cytokine 1 (MIC‐1), may act as both a tumor suppressor and promotor and, by regulating NF‐κB and macrophage signaling, promote early prostate carcinogenesis." (PMID 33784024, 2021). "GDF15 was increased by the presence of a tumor in the C26 model irrespective of age, increased in aged LLC/N and LLC/J mice, and increased in PBS/N mice upon aging." (PMID 35008253, 2021). "Research in mouse xenograft models demonstrated that IGF2BP1 inhibits cell proliferation, tumour growth and tumour metastasis of breast cancer by binding to the 3′UTR of GDF15 mRNA, while other research showed that IGF2BP1 does not affect tumour growth or size." (PMID 34044876, 2021). "Moreover, combined inhibition of both GDF15 and EGR1 showed significantly decreased tumor volume compared to inhibition of EGR1 or GDF15 alone." (PMID 34681812, 2021). "We noted that the expression of miR-216a presented a negative correlation with GDF15 in COAD tumor tissue." (PMID 34948431, 2021). "Since GDF-15 transgenic mice developed more lung metastases and distant organ metastases, metastasis formation does not seem to depend on the size of the primary tumor." (PMID 32508832, 2020). "In this regard the “immune cell repellent” GDF-15 which acts at a critical stage of the anti-tumor immune response not addressed by other checkpoints represents a most promising target." (PMID 32508832, 2020). "This also demonstrated that the tumor size reduction that was present in the TRAMPfmsmic-1 cohort was abolished in the TRAMPfmsmic/rag1-/- group that overexpressed GDF15 but also lacked adaptive immunity." (PMID 32502202, 2020). "Our findings revealed a strong relationship between serum GDF-15 concentrations and the disease spectrum (ranging from SMM to ISS stage III MM), as well as correlations between circulating GDF-15 and indices of tumor burden (albumin, β2-microglobulin), which fall in line with earlier reports (; J.)." (PMID 33144847, 2020). "Of note were GDF15 and AGR2, which are purportedly involved in tumour progression." (PMID 33000006, 2020).
tumor (continued). "On this occasion, to ensure that GDF15 was not acting by altering primary tumor cell implantation, the commencement of treatment was delayed for 3 days after which muGDF15 (0.5 ug/g BW/day) or vehicle via mini-osmotic pump was commenced." (PMID 32502202, 2020). "We found that TK1 can promote LUAD tumor growth and metastasis in a non-canonical manner by activating Rho GTPase activity and growth and differentiation factor 15 (GDF15) expression." (PMID 31589613, 2019). "In this study, we also found that serum GDF15 in early-stage EOC patients (FIGO stage I/II) were dramatically higher than healthy subjects, and the serum GDF15 remained elevated with the clinical stage of the tumor, compared to controls." (PMID 29580231, 2018). "For example, IGF2BP1 expression might upregulate RGS4 mRNA and inhibit tumor cell proliferation and invasion, while downregulate GDF15, IGF2, and PTG2 mRNAs and lead to suppression of tumor cell proliferation and invasion." (PMID 29954406, 2018). "Considering the relationship of EGFR with angiogenesis, we hypothesized that GDF15 secreted from chemotherapy damage to tumor cells could promote neo‐angiogenesis after TACE treatment, eventually leading to the residual tumor progression." (PMID 29383859, 2018). "GDF15 also stimulated the phosphorylation of Smad2, but the GDF15-induced tumor sphere forming efficiency was not significantly affected by treatment with SB431542, an inhibitor of the TGFβ signaling." (PMID 28206960, 2017). "GDF15 serves as a negative CRC prognostic marker, and high levels of GDF15, both in tumor tissues and plasma, correlate with an increased risk of recurrence and reduced overall survival." (PMID 29258163, 2017). "Researchers investigated the effect of GDF15 loss in vivo on hepatocellular carcinogenesis and found that genetic ablation of GDF15 had no apparent effect on the tumor formation, growth or invasiveness in a diethylnitrosamine-induced HCC mouse model." (PMID 28199981, 2017). "Our previous study showed a predominant expression of GDF15 in tumor nest not in stoma in CRC with a heterogeneous staining pattern." (PMID 26497212, 2016). "Analyzing subgroups in 62 DGC patients, GDF15 correlated with tumor invasion and was significantly higher in lymph node metastasis positive patients (N0, 885 ± 354 pg mL−1 vs. N1−3, 1,415 ± 635 pg mL−1)." (PMID 26892343, 2016). "To provide additional evidence that the identified genes were involved in chemoresistance, we further analyzed the role of the cytokine GDF15 during A2780 and A2780cis tumor growth with and without carboplatin treatment." (PMID 25490861, 2015). "Median baseline GDF-15 level was not related to tumor stage (stage 2 disease: median 373.0 pg/mL (range 197.6–1935.0; n = 30), stage 3&4 disease: median 486.4 pg/mL (range 186.8–1875.9; n = 11); P = 0.40)." (PMID 25590623, 2015). "Next, we compared the DcR3 and GDF15 serum concentrations form our ESI MS method with values obtained by an independent technique (ELISA), as well as with the gene expression of the two biomarkers in tumour sections of the same patients, measured by qPCR." (PMID 25823874, 2015). "In detail, A2780, nontransduced and shTRC1-A2780cis tumors showed a tumor growth inhibition between 33% and 37.5%, while GDF15 knockdown in A2780cis resulted in 50% tumor growth inhibition during vehicle treatment." (PMID 25490861, 2015). "SL exposure also induced changes in the expression of genes involved in metabolic functions in tumor and stem cells (ALDH1B1, ABCB1, SLC3A2, SLC44A2, SLC31A2, SLC7A11, CYP24A1, PTGS2/COX2, PPRC1), cytokines (CCL3L3, GDF15) and growth and differentiation factors (PGF, TGFBR11 and FOXD1)." (PMID 24742967, 2014). "Although GDF-15 is a member of the TGF-β superfamily and TGF-β has been confirmed to inhibit DC maturation and function, little is known about the interaction between GDF-15 and immune cells in the tumor microenvironment." (PMID 24236027, 2013).
tumor (continued). "In parallel, upon RUNX2 knockdown, we have observed a predominant and strong downregulation of gene nodes known to be implicated in EOC tumorigenesis (PTGS1/COX1, FGF2, IL1A, Sapk, C/ebp, SELE, UBQLN1, PSAT1, ALDH1A1, GDF15, MTHFD2), including EOC tumor invasion/metastasis (MMP1, MMP13, Creb);." (PMID 24124450, 2013). "To validate the role of GDF-15 in tumor progress, we used a GDF-15 polyclonal antibody to block the GDF-15 induced maturation and the result revealed that the antibody abolished the effect of GDF-15 on inhibiting CD83, CD86 and HLA expression on mDCs in vitro." (PMID 24236027, 2013). "Tumour oncogenes include SPP-1, MITF, CITED-1, GDF-15, c-Met, and HOX loci." (PMID 23091727, 2012). "In this study, we demonstrated a higher recurrence rate in patients curatively operated for CRC stages I–III with moderate or high intensity of GDF15 expression, compared with tumours with no or low intensity of GDF15 expression." (PMID 21468045, 2011). "Moreover, heterogeneity and tumour‐stroma crosstalk, particularly the interaction of CAFs with tumour cells via GDF15/RSPO3, which fosters an immunosuppressive microenvironment around tumour cells, require further confirmation through additional functional experiments." (PMID 40292733, 2025). "Growth/differentiation factor 15 (GDF15), also known as macrophage inhibitory cytokine-1 (MIC1) and nonsteroidal anti-inflammatory drug-activated gene-1 (NAG-1), is considered as a cachexia factor and has been used as a biomarker for tumor diagnosis and prognosis." (PMID 41203604, 2025). "In addition, CAFs promote tumor growth and invasion by secreting several cytokines, exosomes, and growth factors, such as leukemia inhibitory factor (LIF) and growth differentiation factor 15 (GDF15)." (PMID 40686923, 2025). "In our study, we demonstrated that the lack of a statistically significant difference in GDF15 expression between tumor tissue and normal tissue adjacent to the tumor may suggest similar levels of activity of this protein in both types of tissue." (PMID 40725563, 2025). "Furthermore, GDF15 is an important downstream component of the C2 domain‐containing phosphoprotein (CDP138), which impacts the TGFβ/SMAD signaling pathway, essential for controlling tumor resistance to radiation and its potential to metastasize." (PMID 39083441, 2025). "This suggests that GDF15 may capture unique biological processes potentially related to tumor-induced systemic effects that are not reflected by traditional histopathological or molecular markers." (PMID 40725563, 2025). "Additionally, investigating the proteomic effects of DJ-1, GDF15, and MFGE8, as well as their interactions with the tumour microenvironment, could provide a more comprehensive understanding of the clinical relevance of their expression profiles." (PMID 41009755, 2025). "This suggests that the prognostic relevance of GDF15 may stem from its functional role in the tumor microenvironment and systemic signaling, rather than its differential abundance alone." (PMID 40725563, 2025). "This suggested that the GDF15-mediated enhancement of HNSCC oxidative stress activity might originate from exogenous signals rather than GDF15 secreted by tumor cells themselves." (PMID 41035818, 2025). "GDF15 does not affect hepatoma carcinoma cell growth but affects the tumor immune microenvironment." (PMID 38704691, 2024). "Compared to non-cachexic MC38 tumor cells, it was found that GDF-15 concentration in tumor tissue, serum exosomes, and muscle tissue of C26 tumor-bearing mice was higher, and GDF-15 concentration in C26 cells and exosomes was significantly higher than in M38 cells and exosomes." (PMID 38689293, 2024). "Moreover, GDF-15 knockdown did not modify the ability of EHE cells to growth as tumor xenografts in mice." (PMID 39283723, 2024).
tumor (continued). "Compared with healthy controls, serum levels of GDF-15, a member of the TGF-β superfamily, were remarkably upregulated in mCRC patients and had the same sensitivity as the standard tumor marker CEA, indicating that GDF-15 could be an effective biomarker in mCRC patients." (PMID 36430910, 2022). "A long list of tumor-borne, often proinflammatory factors, including interleukin-6 (IL-6), parathyroid hormone–related protein (PTHrP), leukemia inhibitory factor (LIF), zinc α-glycoprotein, or growth differentiation factor-15 (GDF-15), trigger CAC in mouse models." (PMID 35210363, 2022). "In addition, we found that these ligands secreted by hypoxia-related GBM cell types, namely, MES1-like tumor cells, MES2-like tumor cells, and TAM-1, may stimulate angiogenesis via, for example, ADM, ANGPTL4, GDF15, and VEGFA." (PMID 35669791, 2022). "Interestingly, in the JHU-LNCaP-SM xenografted mice, PSA levels did not correlate with the tumor volumes (r: 0.50, p = 0.40) whereas GDF-15 positive correlation with tumor sizes was significant (r: 0.83, p = 0.0154)." (PMID 36261691, 2022). "The expression of miR-216a presented a negative correlation with GDF15 in COAD tumor tissue." (PMID 34948431, 2021). "GDF-15 is cleaved from a propeptide by furin-like proteases before its secretion, but this intracellular cleavage from a propeptide does not process efficiently in tumor tissue." (PMID 34150865, 2021). "In addition, CMKLR1 was found to correlate with GDF-15 and VEGF-A levels in CRC tumor-free margin." (PMID 35008289, 2021). "Further, in-depth analysis of TCGA-PRAD data revealed significantly higher gene expression profiles for SLC12A2 (P = 0.025), DDAH1 (P < 0.0001), NDRG1 (P = 0.0013), APOE (P < 0.0001), YWHAZ (P = 0.0385), and GDF15 (P < 0.0001), in PCa tumor tissue compared with non-tumoral adjacent tissue." (PMID 33483585, 2021). "As opposed to the evident epidemiological data linking GDF-15 with poor survival, studies exploring autocrine effects in tumor cells have, however, reached no consensus as to whether GDF-15 acts as a tumor promoter or suppressor." (PMID 32508832, 2020). "Similarly, the role of GDF-15 in shaping the tumor microenvironment at very early tumor stages is unlikely to be attributable to a CNS-mediated systemic change of metabolism." (PMID 32508832, 2020). "We found that GDF15 induced protection from tumor growth was reversed by lack of adaptive immunity." (PMID 32502202, 2020). "Finally, although alterations in GDF-15 were shown in Caucasian and Asian tumor patients, there is little evidence regarding racial diversification in CAD and HF." (PMID 31252588, 2019). "Nevertheless, expression of GDF-15 is not the same for all GBM cells in the tumor." (PMID 29467963, 2018). "Among them, GDF15, but not TGFβ, clearly induced tumor spheres (2/8 samples)." (PMID 28206960, 2017). "However, the GDF15-induced tumor sphere formation was not significantly affected by treatment with SB431542." (PMID 28206960, 2017). "In addition to following the tumor growth, we determined whether MIC-1/GDF15 might also affect PCa grade, by comparing histopathological scores in TRAMP and double transgenic TRAMPfmsmic-1 prostate tumors." (PMID 22952779, 2012). "The paradoxical observation that high GDF15 expression in the TMA cohort is associated with less advanced TNM and pT stages yet correlates with poorer overall survival, may also reflect the systemic effects of GDF15 that are not directly captured by local tumor characteristics." (PMID 40725563, 2025).